SNORA16A (small nucleolar RNA, H/ACA box 16A )
Synonyms: ACA16
Gene: Small nucleolar RNA gene on chromosome 1 (28,580,920 to 28,581,054, reverse strand). Ensembl gene ENSG00000280498.
Gene Ontology:
Biological process: RNA processing
Cellular component: nucleolus
Homologues: Orthologues: chimpanzee SNORA16A (100% identical), macaque SNORA16A (100% identical), pig SNORA16A (93% identical). Paralogues in human: SNORA16B (87% identical).